PRL (prolactin)
Diseases named in the same sentence as PRL in open-access papers (continued):
Sharing a sentence is not in itself a finding about the gene and the disease.
Ovarian tumors (4 papers, 2013 to 2025). "In both cases, the pituitary gland appeared normal on MRI, the PRL level dropped after the ovarian tumors were surgically removed, and immunohistochemistry of the removed ovarian tissue showed that the tumors had been positive for PRL." (PMID 39928792, 2025). "We report a lady who presented with galactorrhoea and a large ovarian tumour that was found to secrete high levels of prolactin." (PMID 24616762, 2013). "As extensive expression of PRLR was found in HCMV-infected ovarian tumors, and the PRL/PRLR axis can promote tumor growth, this may provide yet another mechanism by which HCMV can promote disease progression of cancer." (PMID 32121009, 2020).
retinal degeneration (4 papers, 2020 to 2024). Degeneration of the retina. "Additional evidence has identified PRL as a trophic factor that regulates glial-neuronal interactions and protects against retinal degeneration." (PMID 35921360, 2022). "This study now confirms and further extends these findings by identifying novel short PRL isoforms expressed in the retinas of two naturally occurring canine models of inherited retinal degeneration, one of which is expressed also in humans." (PMID 33432105, 2021). "Our results call for further investigations into the role of this novel PRL isoform in retinal degeneration." (PMID 33432105, 2021). "Further studies will be directed at identifying the function of this PRL isoform in retinal degeneration." (PMID 33432105, 2021). "In the current study, we have further examined the expression of PRL mRNA in dog retinas during retinal degeneration in an attempt to understand its potential role in photoreceptor cell survival/death." (PMID 33432105, 2021). "PRL plays a protective role in light-induced retinal degeneration and in diabetic retinopathy." (PMID 39294136, 2024). "In addition, the sustained expression of PRL throughout the course of retinal degeneration could provide a large therapeutic window aimed at modulating its function." (PMID 33432105, 2021). "Interestingly, DMF treatment only prevented retinal degeneration after Li-PRL, but not after ONC." (PMID 33519681, 2020).
teratoma (4 papers, 2019 to 2025). A non-seminomatous germ cell tumor characterized by the presence of various tissues which correspond to the different germinal layers (endoderm, mesoderm, and ectoderm). "Neoplasms that contain other benign tissues can also be detected, and these neoplasms include teratomas composed of thyroid tissue, namely, “struma ovarii”; carcinoid tumors; and immature teratomas known as adenomas that produce corticotrophin or prolactin." (PMID 31721911, 2019). "Pituitary hormone-coding PRL and GNRH1 peaked in teratoma, while SHBG mRNA levels were the highest in yolk sac tumors." (PMID 40011822, 2025).
tuberculosis (4 papers, 2023 to 2026). A chronic, recurrent infection caused by the bacterium Mycobacterium tuberculosis. "In turn, prolactin significantly modulates the cytokine response in tuberculosis, increasing inflammatory activation of macrophages and promoting apoptotic processes in granulomas." (PMID 39981081, 2025). "Mycobacterial proteins in experiment strongly stimulate paracrine prolactin production in macrophages, which may contribute to the mechanism of hyperprolactinemia in tuberculosis." (PMID 39981081, 2025).
Uterine leiomyoma (4 papers, 2020 to 2024). The presence of a leiomyoma of the uterus. "Ectopic prolactin production has been reported from tumors such as a leiomyoma of the uterus, a gonadoblastoma, an ovarian teratoma, a perivascular epithelioid cell tumor, a uterine cervical carcinoma, and a colorectal adenocarcinoma." (PMID 39449742, 2024).
abscesses (3 papers, 2024 to 2026). "The presence of abscesses during treatment and elevated plasma prolactin levels was linked to longer disease duration." (PMID 41871228, 2026).
AIDS (3 papers, 2023 to 2025). A syndrome resulting from the acquired deficiency of cellular immunity caused by the human immunodeficiency virus (HIV). "Studies indicate that serum PRL levels in AIDS patients are significantly elevated compared to those of seronegative homosexual men and healthy controls." (PMID 41476991, 2025). "Indeed, it has been shown that mean basal serum GH, prolactin, and testosterone concentrations are similar in subjects positive for HIV (with or without AIDS) as compared to controls, whereas the basal serum concentrations of TSH, LH, ACTH, and cortisol are increased in subjects with AIDS." (PMID 36838326, 2023). "Research indicates that the mean basal serum levels of GH, PRL, and testosterone are comparable between HIV‐positive individuals (regardless of AIDS status) and healthy controls." (PMID 41476991, 2025).
anxiety disorder (3 papers, 2022 to 2024). A category of psychiatric disorders which are characterized by anxious feelings or fear often accompanied by physical symptoms associated with anxiety. "The prolactin and estrogen signaling pathways have been extensively studied in the field of anxiety disorders." (PMID 35624976, 2022). "Considering the high prevalence of anxiety disorder in women, further analysis of the estrogen and prolactin pathways has practical significance in the treatment of anxiety disorder." (PMID 35624976, 2022). "↓ mFG score, LH, LH/FSH, AMH, Total testosterone, FI, FBG, HOMA-IR, TC, TG, LDL, VLDL, TC/HDL, trait anxiety (STAI)↑ HDL, menstrual cycle frequency and quality of life (PCOSQ)↔ weight, BMI, WC, WHR, FSH, Prolactin, and state anxiety.Adverse events not reported." (PMID 38818503, 2024).
Atrophy (3 papers, 2013 to 2025). Any weakening or degeneration, especially through lack of use. "Besides, the presence of PRL lesions in PPMS was associated with subcortical atrophy mainly thalamus and pallidum volumetry." (PMID 40131429, 2025). "Considering the immunomodulatory role of PRL upon the thymus and the effects caused by GCs, weinvestigated herein the role of PRL during thymic atrophy and whether intrathymic cross-talk betweenPRL/GC-mediated circuitries might influence the outcome of the T. cruzi-inducedthymus atrophy." (PMID 24324845, 2013).
autism spectrum disorder (3 papers, 2021 to 2024). A spectrum of developmental disorders that includes autism, and Asperger syndrome. "We investigated the association between genetic variations in pharmacodynamic genes and risperidone-induced increased prolactin levels in children and adolescents with autism spectrum disorder (ASD)." (PMID 34690776, 2021).
benign breast disease (3 papers, 1987 to 2011). "Associations of PRL levels with benign breast disease have been mixed and may depend on the particular underlying pathologic condition leading to the development of benign breast disease." (PMID 20736944, 2010). "Other comparisons of strata for menstrual and reproductive factors, personal history of benign breast disease and family history were not related to significant differences in PRL levels." (PMID 20736944, 2010).
benign breast tumors (3 papers, 1979 to 2023). "The role of prolactin (PRL) and its receptors in the initiation and development of benign breast tumors (BBT) has not been sufficiently studied." (PMID 34945164, 2021).
cardiomyopathy (3 papers, 2019 to 2023). A disease of the heart muscle or myocardium proper. "Five studies compared levels of biomarkers in PPCM to levels in other types of heart disease, and found that unlike other cardiomyopathies, PPCM exhibits increased levels of PRL, miRNA 146a and PlGF." (PMID 33060142, 2020).
chronic headache (3 papers, 2012 to 2025). "Interestingly, there are also reports of SUNCT exacerbations after the administration of cabergoline, suggesting that the dopamine-prolactin axis is important in the pathophysiology of this headache syndrome." (PMID 23050176, 2012).
dependence (3 papers, 2021 to 2025). "Additionally, this group displayed significantly lower baseline PRL levels than those with DA dependence." (PMID 39904877, 2025).
ductal carcinoma (3 papers, 2003 to 2010). "In case-only analyses, higher PRL levels were more strongly associated with lobular compared with ductal carcinoma among postmenopausal women (P=0.02)." (PMID 20736944, 2010). "These considerations and our present results, suggest that autocrine/paracrine GH and/or PRL in the reactive stroma of ductal carcinoma may be inducers of SOCS gene expression in vivo." (PMID 12888825, 2003).
Epstein-Barr virus infection (3 papers, 2017 to 2021). An infection that is caused by Epstein-Barr virus. "The top enriched pathways including Epstein-Barr virus infection (corrected P-values = 1.61E-3), Prolactin Signaling Pathway (corrected P-values = 1.71E-3), G alpha 13 Pathway (corrected P-values = 1.71E-3), and G alpha q Pathway (corrected P-values = 5.22E-3)." (PMID 29207666, 2017).
experimental autoimmune encephalomyelitis (3 papers, 2015 to 2025). An autoimmune demyelinating disease of the central nervous system that is produced experimentally in animals by the injection of homogenized brain or spinal cord in Freund's adjuvant. "Preclinical studies suggest that reduction of prolactin levels via treatment with dopamine D2 agonists (bromocriptine and dihydroergocryptine) reduces severity of experimental autoimmune encephalomyelitis (EAE), an animal model of MS." (PMID 25889599, 2015). "Here, we sought to determine whether recombinant prolactin could alter the course of experimental autoimmune encephalomyelitis (EAE), an inflammatory animal model of MS." (PMID 25889599, 2015). "Broad evidence since the 1970s has demonstrated that PRL can stimulate cells of both innate and adaptive immune systems and therefore PRL has long been considered a potentially detrimental agent in MS and experimental autoimmune encephalomyelitis (EAE), the animal model for this disease." (PMID 27918427, 2016). "In the experimental autoimmune encephalomyelitis (EAE), a widely used MS animal model, plasma prolactin levels correlate with disease severity." (PMID 40242760, 2025).
Fanconi anemia (3 papers, 2022 to 2025). Fanconi anemia (FA) is a hereditary DNA repair disorder characterized by progressive pancytopenia with bone marrow failure, variable congenital malformations and predisposition to develop hematological or solid tumors. "Notable pathways included the prolactin signaling pathway, proteoglycans in cancer, Fanconi anemia pathway, PI3K−Akt signaling pathway, ErbB signaling pathway, and MAPK signaling pathway, among others." (PMID 40356980, 2025). "The KEGG analysis results were mainly enriched in the hippo signaling pathway, prolactin signaling pathway, homologous recombination, vasopressin-regulated water reabsorption, and Fanconi anemia pathway." (PMID 35368696, 2022). "The genes in these three modules revealed significant enrichment for pathways related to ovarian development, such as the oxytocin signaling pathway in the saddlebrown module, prolactin signaling pathway in the paleturquoise module, and Fanconi anemia signaling pathway in the greenyellow module." (PMID 39062708, 2024).
glaucoma (3 papers, 2018 to 2022). Increased pressure in the eyeball due to obstruction of the outflow of aqueous humor. "Identified gene transcripts were involved in several pathways, some implicated in glaucoma before (e.g., TGF-β and neurotrophin signaling), whereas others are new (e.g., prolactin and apelin signaling)." (PMID 34156425, 2021). "In advanced glaucoma, may be possible obtain good results with MP-3 microperimetric biofeedback, with the goal to activate and train new PRL to improve several functional parameters as: fixation stability, BCVA, reading speed and consequently quality of life." (PMID 36207353, 2022).
gonadoblastoma (3 papers, 2013 to 2025). A mixed germ cell/sex cord-stromal tumor characterized by the presence of large germ cells which resemble seminoma cells and small cells which resemble Sertoli or granulosa cells. "Hoffman and colleagues reported the first ever well-documented case of ectopic prolactin secretion secondary to a gonadoblastoma." (PMID 24616762, 2013).
Huntington disease (3 papers, 2016 to 2025). Huntington disease (HD) is a rare neurodegenerative disorder of the central nervous system characterized by unwanted choreatic movements, behavioral and psychiatric disturbances and dementia. "There were five different pathways in the level‐3 KEGG pathway functional prediction, including the Huntington disease, lipoic acid metabolism, thyroid hormone synthesis, arachidonic acid metabolism, and prolactin signaling pathways." (PMID 40365748, 2025).
Hypercholesterolemia (3 papers, 2018 to 2022). An increased concentration of cholesterol in the blood. "Eighty-six patients experienced at least one adverse drug reaction (ADR), accounting for a total of 238 specific reactions, with the most frequent being weight gain (n = 34), increased serum prolactin levels (n = 21), hyperphagia (n = 20), and hypercholesterolemia (n = 14)." (PMID 32265749, 2020).
hyperplasia (3 papers, 2016 to 2022). An abnormal increase in the number of cells in an organ or a tissue with consequent enlargement. "The second-generation GEMMs were born in 1997 with the Mt-PRL, a mouse model created to further study the role of prolactin (PRL) in prostate hyperplasia; the PRL ectopic expression has been inducted by Metallothionein-1 (Mt-1) promoter." (PMID 27294148, 2016). "PRL over-expression in luminal prostate cells using the prostate-specific probasin promoter (Pb–PRL mice) was shown to reproduce these phenotypes without altering androgen serum levels, indicating that prostate hyperplasia in these models was not the results of androgen elevation." (PMID 30984003, 2019).
leukocytosis (3 papers, 2022 to 2024). "A study conducted in Turkey from 1 March 2020 to 1 April 2021 in a group of 80 patients with systemic candidiasis revealed increased prolactin, ferritin, and leukocytosis among patients with candidemia." (PMID 39458399, 2024). "Serum leukocytosis and elevated prolactin levels were commonly seen in both groups." (PMID 35690663, 2022).
lipoma (3 papers, 2015 to 2022). A benign, usually painless, well-circumscribed lipomatous tumor composed of adipose tissue. "Therefore, the effect from menin loss on the expression of prolactin gene family is not relevant in the context of MEN1-associated human lipoma." (PMID 26229531, 2015).
liver fibrosis (3 papers, 2022 to 2025). "Therefore, we conducted this study to investigate the association between serum PRL levels and the risk of MAFLD and liver fibrosis stratified by different PRL subgroups." (PMID 35222274, 2022). "Multiple-adjusted odds ratios (AORs) and 95% confidence intervals (95% CI) for liver fibrosis, according to serum PRL quartiles: results of binary logistic regression analysis in different models." (PMID 35222274, 2022). "The present study revealed a J-shaped association between serum PRL levels and the risk of MAFLD and liver fibrosis in female participants with T2DM." (PMID 35222274, 2022). "Although a close relationship between serum PRL and hepatic lipid accumulation is generally accepted, little is known about the correlation of serum PRL with the risk of incident MAFLD and liver fibrosis in individuals with T2DM." (PMID 35222274, 2022). "Although the exact mechanisms underlying such gender-specific association between PRL, MAFLD, and liver fibrosis remain unclear, several underlying reasons may account for this apparent discrepancy between males and females." (PMID 35222274, 2022). "Such associations were also found between serum PRL and liver fibrosis in females but not in males." (PMID 35222274, 2022). "To investigate the relationship between serum PRL and MAFLD and hepatic fibrosis in type 2 diabetic patients, we divided patients into NP and HP groups." (PMID 35222274, 2022). "This study used network pharmacology methods to identify potential targets of BSHXHZF for treating WD liver fibrosis, including tanshinone IIA, quercetin, flavonoids, α-amyrin, and hesperidin, as well as signaling pathways, such as IL-17, HIF-1, prolactin, and NF-κB." (PMID 40557038, 2025). "In binary logistic regression analysis, we found a significant J-shaped association between serum PRL levels and the risk of MAFLD and hepatic fibrosis in females with T2DM but not in males." (PMID 35222274, 2022). "High-normal serum PRL appeared to be a protective factor for MAFLD and liver fibrosis." (PMID 35222274, 2022). "When these findings were combined, they revealed a significant J-shaped relationship between serum PRL levels and the risk of MAFLD and liver fibrosis in female but in not male patients with T2DM." (PMID 35222274, 2022). "In the present study, we observed a J-shaped association between serum PRL and the risk of MAFLD and liver fibrosis in females with T2DM but not in males, indicating that PRL may be relevant to MAFLD and its progression in a gender-specific manner." (PMID 35222274, 2022). "However, the ORs (95% CI) for MAFLD and hepatic fibrosis did not change significantly across serum PRL quartiles in males." (PMID 35222274, 2022). "We observed a J-shaped association between serum PRL and the risk of MAFLD and liver fibrosis in females but not in males with T2DM, indicating that PRL may be relevant to MAFLD and its progression in a gender-specific manner." (PMID 35222274, 2022).
neuroleptic malignant syndrome (3 papers, 2016 to 2025). Neuroleptic malignant syndrome (NMS) is an idiosyncratic condition associated with administration of antipsychotic and other central dopaminergic blockers, and characterized by hyperthermia, muscular rigidity, autonomic dysfunction and altered consciousness. "Trainees most commonly mentioned EPSEs, including specifically tardive dyskinesia, neuroleptic malignant syndrome, prolactin elevation, anticholinergic side-effects, QTc prolongation, cardiac toxicity and sudden death." (PMID 27087995, 2016). "From the perspective of antipsychotic drug adverse reactions, long-term use of super doses may lead to tardive dyskinesia, increased prolactin levels, toxic liver damage, bone marrow suppression, seizures, allergic rashes, exfoliative dermatitis, and neuroleptic malignant syndrome." (PMID 39902243, 2024).
oncocytoma (3 papers, 2010 to 2021). "We collected ACTH-PA, silent ACTH-PA, GT-PA, GH-PA, PRL-PA, GH-PRL-PA, oncocytomas, NC-PA and normal pituitary glands from patients or donors and subjected these samples to metabolomic analysis." (PMID 31455412, 2019). "Notably, the two clusters (Cluster 1: PRL-PA/GH-PA/GH-PRL-PA, and Cluster 2: GT-PA/NC-PA/oncocytoma) were again automatically formed." (PMID 31455412, 2019).
ovarian hyperstimulation syndrome (3 papers, 2015 to 2025). A complication of ovulation induction in infertility treatment. "Other study showed that cabergoline in PCOS patients can provide better ovarian response, reduced the risk of ovarian hyperstimulation syndrome (OHSS), and decreased serum prolactin concentration with no increase in pregnancy rate." (PMID 25999998, 2015).
periodontal disease (3 papers, 2023 to 2025). "Additionally, all antipsychotics have the potential to reduce bone density and increase the susceptibility to periodontal disease, but ‘prolactin‐inducing’ antipsychotics have a greater propensity for alveolar bone resorption." (PMID 40329580, 2025). "According to our results, it could be concluded that all antipsychotics contribute to the progression of periodontal disease, with a higher risk for prolactin-inducing antipsychotics." (PMID 37875841, 2023). "Moreover, it is the first study to compare the effect of antipsychotic medications on periodontal disease in terms of their effect on serum prolactin levels." (PMID 37875841, 2023).